RHOBTB1 (Rho related BTB domain containing 1)
Synonyms: KIAA0740
Tractability: Antibody: its Gene Ontology location is reachable by antibodies, with medium confidence. PROTAC: ubiquitination databases record sites on it.
Gene: Protein-coding gene on chromosome 10 (60,869,438 to 61,001,441, reverse strand). Ensembl gene ENSG00000072422.
Subcellular location (Human Protein Atlas): Nucleoplasm; Cytosol
Pathways (Reactome):
Signal Transduction: RHOBTB1 GTPase cycle
Gene Ontology:
Molecular function: protein binding; G protein activity; GTP binding; GTPase activity
Biological process: actin filament organization; establishment or maintenance of cell polarity; regulation of cell shape; small GTPase-mediated signal transduction
Cellular component: cytoplasmic vesicle; cytoskeleton; endosome membrane
Genetic constraint (gnomAD): Loss-of-function variants: 37 observed, 71.59 expected, observed/expected ratio (o/e) 0.52, 90% interval 0.4 to 0.68. The upper end of that interval is the gene's LOEUF score, 0.68, which puts it in group 2 of 6, group 1 being the genes least tolerant of losing a copy. Missense variants: 795 observed, 937.98 expected, observed/expected ratio (o/e) 0.85, 90% interval 0.8 to 0.9. Synonymous variants: 319 observed, 352.47 expected, observed/expected ratio (o/e) 0.91, 90% interval 0.82 to 0.99.
Homologues: Orthologues: chimpanzee RHOBTB1 (99% identical), macaque RHOBTB1 (98% identical), rabbit RHOBTB1 (95% identical), guinea pig RHOBTB1 (94% identical), pig RHOBTB1 (93% identical), dog RHOBTB1 (93% identical), mouse Rhobtb1 (89% identical), rat Rhobtb1 (89% identical), tropical clawed frog rhobtb1 (80% identical), zebrafish rhobtb1 (73% identical). Paralogues in human: RHOBTB2 (70% identical), RAC1 (13% identical), RAC3 (13% identical), CDC42 (13% identical), RAC2 (13% identical), RHOQ (12% identical), RHOT1 (12% identical), RHOG (12% identical), RHOA (12% identical), RHOU (11% identical), RHOJ (11% identical), RHOT2 (11% identical), and 10 more.
Diseases named in the same sentence as RHOBTB1 in open-access papers:
RHOBTB1 is named in the same sentence as 17 diseases in open-access papers, as found by Europe PMC text mining. Sharing a sentence is not in itself a finding about the gene and the disease. The quoted sentences say what the papers report.
Hypertension (5 papers, 2020 to 2023). The presence of chronic increased pressure in the systemic arterial system. "PPARG mutations cause hypertension in humans, and RhoBTB1 has been associated with BP." (PMID 35358093, 2022). "However, in hypertension caused by smooth muscle–specific, dominant-negative PPARγ mutation, RhoBTB1 reversed hypertension by improving vasodilation." (PMID 35358093, 2022). "This study was designed as a reversal study, that is, we tested the effectiveness of RhoBTB1 to reverse established hypertension, just as pharmacological agents are used to treat a patient presenting with hypertension." (PMID 35358093, 2022). "Our study reveals an important function of RhoBTB1, demonstrates its vital role in antagonizing established arterial stiffness, and further supports a functional and mechanistic separation among hypertension, vascular dysfunction, and arterial stiffness." (PMID 35358093, 2022). "Here, we focused on the protective effects of RhoBTB1 in Ang II–induced hypertension not only because Ang II hypertension represents more systemic and intricate pathologies but also because Ang II decreases RhoBTB1 levels in the vasculature." (PMID 35358093, 2022). "In mice, interference with PPARγ signaling in vascular SMCs results in hypertension, vascular dysfunction, and arterial stiffness; furthermore, Rhobtb1 expression decreases concurrently with these phenotypes." (PMID 35358093, 2022). "RHOBTB1 is a tumor suppressor gene involved in head and neck cancer and is also involved in protecting against hypertension by improving vasodilator function." (PMID 33967749, 2021). "In this study, we assessed whether the cardioprotective effect of RhoBTB1 is active in other forms of hypertension and arterial stiffness." (PMID 35358093, 2022). "We tested the hypothesis that restoring RhoBTB1 can attenuate arterial stiffness, hypertension, and vascular dysfunction in Ang II–treated mice." (PMID 35358093, 2022). "We recently showed that restoring Rhobtb1 expression in vascular SMCs in mice with SMC-specific, dominant-negative PPARγ reversed the hypertension, vascular dysfunction, and arterial stiffness caused by the smooth muscle–specific expression of a dominant-negative mutation of PPARγ." (PMID 35358093, 2022). "Thus, RhoBTB1 efficiently and rapidly reversed established arterial stiffness even during the preservation of hypertension and vascular dysfunction." (PMID 35358093, 2022). "Of note, RhoBTB1 serves as a CRL3 substrate adaptor for the ubiquitination of PDE5, further suggesting that enhanced binding of variant CUL3 with substrate adaptors results in impaired substrate (i.e., RhoA and PDE5) ubiquitination and diminished vascular compliance in FHHt hypertension." (PMID 37845702, 2023). "Perhaps, the downregulation of Rhobtb1 by Ang II may be the product of both mechanisms acting simultaneously, which may be interpreted as attempts to maintain the structural integrity (e.g., stiffness) of arterial wall and prevent aneurysm or rupture under conditions of marked hypertension." (PMID 35358093, 2022). "Mice treated with angiotensin II (Ang II) develop hypertension, arterial stiffness, vascular dysfunction, and a downregulation of Rho-related BTB domain–containing protein 1 (RhoBTB1) in the vasculature." (PMID 35358093, 2022). "RhoBTB1 restoration efficiently and rapidly alleviated arterial stiffness but not hypertension or vascular dysfunction." (PMID 35358093, 2022). "RhoBTB1 attenuates vascular stiffness via actin depolymerization in mice with angiotensin-II-induced hypertension, though it does not reverse the hypertension." (PMID 36134994, 2022).
breast carcinoma (4 papers, 2017 to 2023). "The narratives surrounding RhoBTB1 and RhoBTB2, and their associations with breast cancer, are subjects of intrigue, but their precise roles remain shrouded in mystery." (PMID 37762375, 2023). "Loss of RhoBTB1 expression in breast cancer cells leads to Golgi fragmentation and hence loss of normal polarity." (PMID 28219369, 2017). "Here we find that the loss of expression of RhoBTB1 in T47D breast cancer cells is linked to fragmentation of the Golgi." (PMID 28219369, 2017). "We propose that loss of RhoBTB1 early in breast cancer development promotes loss of normal epithelial polarity through reduced METTL7B expression and Golgi fragmentation." (PMID 28219369, 2017). "We conclude that loss of RhoBTB1 expression in T47D breast cancer cells contributes to a pro-invasion phenotype." (PMID 28219369, 2017). "Loss of RhoBTB1 expression is linked to Golgi fragmentation in breast cancer cells." (PMID 28219369, 2017). "Intriguingly, whereas the normal mammary cell lines had a compact Golgi ribbon, T47D cells showed extreme fragmentation of the Golgi, raising the possibility of a functional link between loss of RhoBTB1 expression and Golgi morphology in this breast cancer line." (PMID 28219369, 2017). "Through various functional studies, it is discerned that a surge in METTL7B expression counteracts the invasive tendencies of breast cancer cells and concurrently rectifies the Golgi disintegration brought on by RhoBTB1 insufficiency." (PMID 37762375, 2023). "In breast cancer cells and patient samples, there is a marked downregulation of RhoBTB1 (Rho-Related BTB Domain Containing 1) expression, hinting at its probable tumor suppressor properties." (PMID 37762375, 2023). "In support of our observations on RhoBTB1 in 3D, RhoBTB1 overexpression has recently been reported to reduce invasion of T47D breast cancer cells." (PMID 31431478, 2019). "Restoration of normal RhoBTB1 levels to T47D breast cancer cells restores Golgi integrity and leads to a dramatic decrease in their invasive capacity." (PMID 28219369, 2017). "Instead, we found that re-expression of RhoBTB1 in T47D breast cancer cells strongly inhibited their invasive capacity in 3D." (PMID 28219369, 2017). "We examined the relative expression of RhoBTB1 and RhoBTB2 in a selection of human breast cancer cell lines (MDA-MB-231, T47D, MCF7) in comparison to two well-characterized normal human mammary epithelial cell lines – MCF10A and HMT-3522 S1." (PMID 28219369, 2017). "Restoration of normal RhoBTB1 expression rescues Golgi morphology and dramatically inhibits breast cancer cell invasion." (PMID 28219369, 2017). "Chemotherapy-induced fatigue may involve downregulation of RHOBTB1 in peripheral blood mononuclear cells of patients with locoregional breast cancer." (PMID 36185995, 2022). "We examined whether restoration of RhoBTB1 expression and normalization of Golgi morphology would affect these processes in T47D breast cancer cells." (PMID 28219369, 2017). "All three breast cancer cell lines had reduced RhoBTB1 expression." (PMID 28219369, 2017). "This interplay implies that RhoBTB1 acts as a brake on METTL7B, ensuring the structural and functional integrity of the Golgi apparatus and curtailing the invasion of breast cancer cells." (PMID 37762375, 2023).
colon cancer (4 papers, 2014 to 2022). "Expression of RHOBTB1 has been found decreased in kidney, breast and stomach tumors in a cancer profiling array, as well as in HNSCCs and in colon cancer tissues." (PMID 27314390, 2016). "The tumor suppressor RhoBTB1, a new target gene of miR-31, is downregulated in colon cancer tissues." (PMID 26307974, 2015). "Moreover, another member of the Rho family, RHOBTB1, was shown to be a target of miR-31 in colon cancer." (PMID 36313626, 2022). "Furthermore, it is reported that miR-31 contributes to the development of colon cancer at least partly by targeting RhoBTB1 (Rho-related BTB domain containing 1)." (PMID 24743265, 2014). "By targeting RhoBTB1, miR-31 could contribute to the development and progression of colon cancer." (PMID 26307974, 2015).
COVID-19 (1 paper, 2023). A disease caused by infection with severe acute respiratory syndrome coronavirus 2. "In the validation dataset, we found consistent metabolic trends in T cells; namely, we found that COVID-19 T cells downregulate key mitophagy genes FUNDC1, PINK1, and CSNK2B and upregulate key Rho GTPase genes RHOA, RHOBTB1, and ARAP3 as well as MTOR compared to HIV-1+ individuals." (PMID 36992700, 2023).
leukemia (1 paper, 2021). A malignant (clonal) hematologic disorder, involving hematopoietic stem cells and characterized by the presence of primitive or atypical myeloid or lymphoid cells in the bone marrow and the blood. "Consistently, three datasets indicated increased RHOBTB2 expression; six datasets and five datasets showed reduced RHOBTB1 and RHOBTB3 expression, respectively, in leukemia compared to normal samples in the ONCOMINE database." (PMID 34074803, 2021).
Myalgia (1 paper, 2021). "From the whole genome sequencing results, potentially functional SNPs in RHOBTB1 and SUSD1 were found to be highly associated with atorvastatin-induced myalgia." (PMID 33967749, 2021).
neuroblastoma (1 paper, 2012). Neuroblastoma (NB) is the most common solid, extracranial childhood tumor. "For example RhoU, RhoBTB1 and especially Rnd2 are expressed in neuroblastoma, while Rnd3 is expressed in HeLa and neuroblastoma." (PMID 22916134, 2012).
osteoporosis (1 paper, 2025). A condition of reduced bone mass, with decreased cortical thickness and a decrease in the number and size of the trabeculae of cancellous bone (but normal chemical composition), resulting in increased fracture incidence. "GSEA confirmed significant enrichment in pathways crucial for osteoporosis development, including mitochondrial gene expression, RHOBTB1 GTPase cycle, and the IL-17 pathway." (PMID 40918403, 2025). "The enrichment of the RHOBTB1 GTPase cycle suggests its potential involvement in mechanisms regulating bone density and strength, which are frequently impaired in osteoporosis." (PMID 40918403, 2025).
prostate carcinoma (1 paper, 2019). A carcinoma that arises from epithelial cells of the prostate gland. "Here we show for the first time that RhoBTB1 depletion induces PC3 prostate cancer cell elongation in 3D matrices and increases invasion through Matrigel." (PMID 31431478, 2019). "We report that RhoBTB1 depletion increases prostate cancer cell invasion and induces elongation in Matrigel, a phenotype similar to that induced by depletion of ROCK1 and ROCK2." (PMID 31431478, 2019).
psoriasis (1 paper, 2020). An autoimmune condition characterized by red, well-delineated plaques with silvery scales that are usually on the extensor surfaces and scalp. "As in psoriasis and cutaneous wound healing, miR-31 is upregulated in cSCC promoting cell proliferation, although the target is different: rho-related BTB domain containing 1 (RhoBTB1)." (PMID 32806619, 2020).
tumor (9 papers, 2015 to 2025). "Multivariate linear regression analysis identified SNPs in 11 genes (Sepsecs, Rhobtb1, Tsen15, Abcc3, Arid5b, Tnr, Dock2, Tti1, Fam81a, Stx6, and Oxr1) that were independently associated with the tumour multiplicities." (PMID 39067134, 2024). "We pooled all 20 genes (Stx6, Ramp1, Traf3ip1, Nckap5, Pfkfb2, Trmt1l, Rprd1b, Rer1, Sepsecs, Rhobtb1, Tsen15, Abcc3, Arid5b, Tnr, Dock2, Tti1, Fam81a, Oxr1, Plxna2 and Tbc1d31) together as the mouse tumour susceptibility gene signature (mTSGS)." (PMID 39067134, 2024). "Many studies have shown that tumor suppressor RHOBTB1 contributes to the proliferation and invasion of cancer." (PMID 36185995, 2022). "Multivariate analyses flagged SNPs in 20 genes (Stx6, Ramp1, Traf3ip1, Nckap5, Pfkfb2, Trmt1l, Rprd1b, Rer1, Sepsecs, Rhobtb1, Tsen15, Abcc3, Arid5b, Tnr, Dock2, Tti1, Fam81a, Oxr1, Plxna2, and Tbc1d31) independently tied to various tumour characteristics, designated as a mTSGS." (PMID 39067134, 2024). "We therefore reverse engineered a static ARACNE mutual information network representing the neighbourhood of RND3, RHOC, RHOBTB1 and RHOBTB2 during the tumour implantation time course." (PMID 26132659, 2015).
cancer (8 papers, 2010 to 2024). A tumor composed of atypical neoplastic, often pleomorphic cells that invade other tissues. "This becomes important when considering the effects of the downregulation of RhoBTB1 and 2 in cancer cells, where loss of one isoform could potentially increase homodimer concentration of the other, in addition to the simpler effects of reducing its own concentration." (PMID 28219369, 2017). "We propose that RhoBTB1 suppresses cancer cell invasion through interacting with ROCKs, which in turn regulate its association with Cullin3." (PMID 31431478, 2019). "Here we show for the first time that a decrease in RhoBTB1 expression leads to changes in cell morphology and increased invasion of cancer cells." (PMID 31431478, 2019). "We propose that RhoBTB1/ROCK complexes could act together to regulate cancer cell morphology and invasion." (PMID 31431478, 2019). "In particular, RhoBTB1 was reported to co-immunoprecipitate with ROCK1 in COS7 cells and to inhibit cancer cell invasion by an unclear mechanism." (PMID 35358093, 2022).
RHOBTB1 also shares sentences with these, for which no sentence is quoted: head and neck carcinoma (2 papers); acute myeloid leukemia (1); aneurysm (1); colorectal cancer (1); lung carcinoma (1).